CDH17 (cadherin 17)
Diseases named in the same sentence as CDH17 in open-access papers (continued):
Sharing a sentence is not in itself a finding about the gene and the disease.
gastric cancer (continued). "We demonstrated that CDH17 nanobody can be used for gastric cancer imaging." (PMID 36435809, 2022). "Having verified that E8 nanobody holds the great targeting ability against CDH17-overexpressing tumor for imaging, we next evaluated whether E8 nanobody could be applied as a drug delivery vehicle to treat gastric cancers." (PMID 36435809, 2022). "Knockdown CDH17 was reported to repress the growth of liver cancer and gastric cancer." (PMID 36435809, 2022). "CDH-17 plays an essential role in cancer cell proliferation, cell adhesion, migration, and invasion; therefore, CDH-17 could be an ideal target molecule for gastric cancer therapy." (PMID 35453596, 2022). "Recently, PET-based detection and monitoring of metastasis cancer has utilized the following antibodies: 111In-labeled anti-CDH17 (gastric cancer), 177Lu-labeled anti-CD55 (lung cancer), and radio-labeled anti-ERBB2 (various labeling, including 89Zr, 64Cu, 111In) (breast cancer)." (PMID 34680307, 2021). "CDH17 is expressed in not only gastric cancer but also colon cancer and pancreatic cancer: the expression ratios of colonic adenocarcinoma, pancreatic ductal adenocarcinoma, pancreatic adenocarcinoma, and cholangiocarcinoma were reported to be 97.3%, 39.3%, 24.1%, and 53.3%, respectively." (PMID 31605356, 2020). "Second, CDH17 expression analysis in gastric cancer specimens was performed with only a small sample size; therefore, further expression analyses using larger numbers of specimens are needed to confirm a role of CDH17-targeted imaging on N-staging in gastric cancer." (PMID 31605356, 2020). "Here, we developed an 111In-labeled anti-CDH17 monoclonal antibody (Mab) as an imaging tracer and performed biodistribution and single-photon emission computed tomography (SPECT)/computed tomography (CT) imaging studies using mice with CDH17-positive gastric cancer xenografts." (PMID 31605356, 2020). "Therefore, CDH17-targeted imaging using 111In-D2101 would be promising for prognostic prediction of gastric cancer patients." (PMID 31605356, 2020). "CDH17 expression in gastric cancer specimens was also analyzed." (PMID 31605356, 2020). "CDH17 expression in gastric cancer specimens was evaluated by immunohistochemistry." (PMID 31605356, 2020). "In ELISA assays, D2101 showed high specificity to CDH17-expressing gastric cancer cells." (PMID 33050602, 2020). "The present study demonstrated that CDH17 is frequently expressed in both primary and metastatic gastric cancer, and that 111In-D2101 has high binding affinity in vitro, high accumulation in CDH17-positive tumors in vivo, and can be visualized by SPECT/CT imaging." (PMID 31605356, 2020). "Therefore, 111In-D2101 is a promising imaging agent for detecting CDH17-positive gastric cancer and is applicable to the clinical setting." (PMID 31605356, 2020). "CDH17 is also reported as a prognostic factor for gastric cancer patients." (PMID 31605356, 2020). "In this study, multiple gene expression arrays of 42 systemic normal tissue samples and 56 gastric cancer samples were used to investigate two adhesion molecules, cadherin 17 (CDH17) and claudin 18 (CLDN18), which are intestinal and gastric markers, respectively." (PMID 27580354, 2016). "Together, these results indicate that CDH17 and CLDN18 are useful target molecules; moreover, their coupling can aid in the comprehensive detection and localization of gastric cancer metastases in vivo to overcome challenges associated with intratumoral heterogeneity." (PMID 27580354, 2016). "In humans, CDH17 is expressed in the fetal liver and gastrointestinal tract but is downregulated in the adult liver and gastrointestinal tract; however, it is upregulated in gastric cancer, esophageal cancer, pancreatic cancer, and hepatocarcinoma." (PMID 25612318, 2015). "It indicated that CDH17 plays an important role in the carcinogenesis of gastric cancer." (PMID 24465527, 2014).
gastric cancer (continued). "CDH17 has been proposed as an oncogene and a useful marker for diagnosis of gastric cancers." (PMID 24465527, 2014). "CDH17 was expressed in 50–78% of gastric cancer tissues with intestinal-type predominance." (PMID 23554857, 2013). "The molecular mechanisms by which CDH17 regulates gastric cancer growth remain to be elucidated." (PMID 23554857, 2013). "In gastric cancer, CDH17 may mediate carcinoma cell interaction with gastric stroma and be involved in the promotion of gastric cancer metastasis by facilitating carcinoma cell migration and re-establishing homophilic cell-cell adhesion in metastasis." (PMID 23554857, 2013). "Our results strongly suggest that gastric cancer patients may benefit from targeted therapy against CDH17, and warrant the exploration and design of potential CDH17 inhibitors." (PMID 23554857, 2013). "We evaluated whether human gastric carcinoma cell lines express CDH17 and thus could be used to further evaluate the potential function this protein." (PMID 23554857, 2013). "We examined whether CDH17 is required for tumor formation and invasiveness in gastric carcinoma cells in a nude mice model." (PMID 23554857, 2013). "Infection of the gastric carcinoma cells by CDH17 shRNA abolished their carcinogenicity in mice." (PMID 23554857, 2013). "Therefore, our findings demonstrate that nanobody conjugates against CDH17 hold great potential for gastric cancer imaging and should be considered preferentially in lieu of conventional antibody for visualization of CDH17-postive gastric cancer." (PMID 36435809, 2022). "These nanobodies could specifically bind to CDH17 protein and CDH17-positive gastric cancer cells." (PMID 36435809, 2022). "Compared with GES-1 and MDA-MB-231 cells, four gastric cancer cell lines showed significant expression of CDH17, and membrane staining of CDH17 can be clearly identified in GC cell lines." (PMID 36435809, 2022). "In the CDH17 immunohistochemical analysis of gastric cancer specimens, the percentage of CDH17-positive primary cancer and positive LN metastasis [primary (+)/LN (+)] was 80%, suggesting that most metastatic regions are positive for CDH17 when the primary regions are CDH17-positive." (PMID 31605356, 2020). "Therefore, CDH17 is a promising therapeutic target for CDH17-positive gastric cancer." (PMID 31605356, 2020). "This study aimed to explore the correlations between cadherin-17 (CDH17) proteinexpression and the clinicopathological features and prognosis of patients withsporadic gastric cancer (GC)." (PMID 26421870, 2015). "Accordingly, we postulate that targeting CDH17 may be used to treat gastric cancer in vivo." (PMID 23554857, 2013). "All five studies identified CDH17 as a key driver of canonical Wnt signalling, directly influencing cancer progression in hepatocellular carcinoma (HCC), gastric cancer (GC), and colorectal cancer (CRC)." (PMID 41155133, 2025). "CDH17 knockdown stable cell lines were established in MKN45 and IM95 gastric cancer cells to confirm the specificity of Nb289 nanobody to CDH17." (PMID 38888519, 2024). "Overexpression of CDH17 is widely reported in various GI cancers, including CRC, gastric cancer, cholangiocarcinoma, hepatocellular carcinoma, pancreatic cancer, neuroendocrine cancer, and esophageal cancer." (PMID 39617741, 2024). "Firstly, the expression levels of CDH17 and HER2 in the same gastric cancer cell line or cancer tissue are distinct." (PMID 36435809, 2022). "The CDH17 and HER2 expression frequencies were evaluated in gastric cancer specimens by immunohistochemistry." (PMID 31605356, 2020). "Cadherin-17 (CDH17) is a membrane protein that mediates cell–cell adhesion and is frequently expressed in adenocarcinomas such as gastric cancer, colorectal cancer, and pancreatic cancer." (PMID 31605356, 2020). "Cadherin-17 (CDH17) is a transmembrane protein that mediates cell–cell adhesion and is frequently expressed in adenocarcinomas, including gastric cancer." (PMID 31605356, 2020).
gastric cancer (continued). "Therefore, CDH17 could be a superior target protein for gastric cancer-specific imaging." (PMID 31605356, 2020). "CDH17 has also been reported to alter MMP9 and MMP2 expression via activation of the NF-kB signaling pathway in gastric cancer." (PMID 31324051, 2019). "It was reported that downregulation of cadherin-17 inactivates WNT signaling and inhibits tumor growth in hepatocellular carcinoma and gastric cancer." (PMID 28197418, 2017). "It was further shown that targeting cadherin-17 inactivated Ras/Raf/MEK/ERK signaling and inhibited cell proliferation in gastric cancer." (PMID 28197418, 2017). "Combination of CDH17 and CLDN18 covered 50 cases out of 56 (89.3%), which indicated that the coupling of markers for CDH17 and CLDN18 provides an opportunity to detect gastric cancer using specific antibodies." (PMID 27580354, 2016). "The most innovative point of this study is that the combination of CDH17 and CLDN18 demonstrated homogeneous and robust expression in more than 90% cases of gastric cancer, even in diffuse-type cases." (PMID 27580354, 2016). "Secondly, just two markers, CDH17 and CLDN18, was sufficient to account for more than 90% of gastric cancer cases." (PMID 27580354, 2016). "Hierarchical clustering classified gastric cancers into three subgroups, CDH17(++)/CLDN18(+/−), CDH17(++)/CLDN18(++) or CDH17(+)/CLDN18(+), and CDH17(−)/CLDN18(++/+/−)." (PMID 27580354, 2016). "Knockdown CDH17 with lentivirus-mediated miRNA inhibited the proliferation, adherence, tumor growth, and metastasis of BGC823 human gastric cancer cells both in vitro and in vivo." (PMID 24465527, 2014). "Herein, CDH17 knockdown decreased β-catenin and GSK-3β phosphorylation, accompanied by a concomitant increase of Rb and reduction of Cyclin D1 in gastric cancer." (PMID 23554857, 2013). "The seven RNAs upregulated in gastric cancer were CLDN18, EPCAM, REG4, BBC3, OLFM4, PPARG, and CDH17, while the two downregulated genes were IFITM1 and HIF1A." (PMID 22929309, 2012). "In addition, CDH17-targeted hybrid imaging has been investigated in preclinical studies of PDAC and gastric cancer." (PMID 41164107, 2025). "CDH17 is expressed in BRCA, HNSC, and a gene in metanephric adenoma and gastric cancer." (PMID 36016607, 2022). "Our anti-CDH17 Mab D2101 radiolabeled with 111In exhibited high levels of tumor uptake and low background levels in the biodistribution and SPECT/CT studies in a CDH17-positive gastric cancer mouse model." (PMID 31605356, 2020). "In the present study, D2101 was radiolabeled with 111In (111In-D2101), and the pharmacokinetics of 1111In-D2101 were evaluated by biodistribution studies in CDH17-positive and CDH17-negative gastric cancer xenograft mice." (PMID 31605356, 2020). "It was demonstrated that downregulation of cadherin-17 induced inactivation of NFkB signaling pathway with the reductions of downstream proteins including VEGF-C and MMP-9 and suppressed proliferation, adherence, and invasion in gastric cancer." (PMID 28197418, 2017). "Intestinal-type CDH17 and gastric-type CLDN18 could be a useful combination to enable coverage of most gastric cancers that show a partial redundancy but primarily specific behavior." (PMID 27580354, 2016). "CDH17 and CLDN18 showed high specificity for gastric cancer cells." (PMID 27580354, 2016). "According to hierarchical clustering applied to the threshold of CDH17 and CLDN18 IHC scores of primary lesions, gastric cancers could be classified into three subgroups." (PMID 27580354, 2016). "Firstly, CDH17 and CLDN18 demonstrated homogeneous immunostaining in gastric cancer tissue." (PMID 27580354, 2016). "IHC scores of CDH17, CLDN18, and CLDN7 expression levels were evaluated semi-quantitatively in TMA-mounted primary lesions (IHC score (Pr)) and lymph node metastases (IHC score (LN)) taken from 106 cases of advanced gastric cancers." (PMID 27580354, 2016). "Combination of CDH17 and CLDN18 markers detected 92.5% of gastric cancer cases (98 of 106 cases)." (PMID 27580354, 2016).
gastric cancer (continued). "In addition to tumor suppressors, we also observed several candidate oncogenes to be expressed at lower levels in EBVaGCs including 4 (CDH17, CDX1, ETV4, and PPP1R1B) known to be over expressed in gastric carcinoma and gastrointestinal cancers." (PMID 23671415, 2013). "Despite these significant clinical findings, the molecular functions of CDH17 remain unknown, and its tumorigenic role in gastric carcinoma has not yet been confirmed." (PMID 23554857, 2013). "Furthermore, the lack of CDH17 expression by healthy stomach tissue similarly suggests that the probe could be valuable in patients with stomach and gastric cancer, but higher levels of expression in the colon may portend challenges in the context of colorectal adenocarcinoma." (PMID 38625402, 2024). "In this study, we selected CDH17 and CLDN18 through mining of systemic microarray gene expression data, based on their high frequency of expression in gastric cancer tissues and absence of expression in other major vital organs." (PMID 27580354, 2016).
colorectal cancer (34 papers, 2013 to 2025). A primary or metastatic malignant neoplasm that affects the colon or rectum. "Claudin-3 (CLDN3) is associated with colorectal cancer progression, while Cadherin-17 (CDH17) correlates with unfavorable prognosis in various cancers." (PMID 40452847, 2025). "A comprehensive analysis was conducted on the Gene Expression Profiling and Interactive Analyses (GEPIA) database to identify antigens as potentially suitable tumor-associated targets for developing BsADCs with CDH17, which should also be highly expressed in colorectal cancer." (PMID 40721409, 2025). "Here, we found that CDH17 and GUCY2C are co-overexpressed in colorectal cancer cells and developed a bispecific antibody-drug conjugate (BsADC) targeting CDH17 and GUCY2C, conjugated with the ferroptosis inducer RSL3 (a GPX4 inhibitor)." (PMID 40721409, 2025). "Previous research has indicated that high CDH17 expression in tumor tissues is correlated with poorer prognosis and survival in patients with colorectal cancer, cholangiocarcinoma, and hepatocellular carcinoma." (PMID 39994505, 2025). "VHH1-CAR-T cells (CDH17-CARTs) eradicated CDH17-expressing NETs, such as gastric, pancreatic and colorectal cancer cells." (PMID 40007813, 2025). "CDH17 is known to activate the Wnt/β-catenin signaling pathway, promoting growth and metastasis in hepatocellular and colorectal cancers." (PMID 39994505, 2025). "The expression of CDH17 typically diminishes in the initial stages of colorectal cancer compared with normal mucosa and increases in advanced cancer stages, particularly in liver metastasis." (PMID 41039222, 2025). "The efficacy was demonstrated using either colorectal cancer cells expressing CDH17 or CDH5-expressing melanoma cells, owing to the high homology of the RGD flanking sequences." (PMID 41039222, 2025). "In conclusion, CDH17 plays a crucial role in maintaining colorectal cancer cell stemness and chemoresistance via LGR5/Wnt/MYC signaling and SLC38A5 expression." (PMID 40595509, 2025). "The resultant biohybrid bacteria can efficiently home to CDH17‐positive tumors, including gastric, pancreatic, and colorectal cancers, and significantly suppress tumor growth upon irradiation." (PMID 38888519, 2024). "The resultant biohybrid bacteria exhibited effective targeting toward gastric, pancreatic, and colorectal cancers, all of which highly expressed CDH17 to varying degrees." (PMID 38888519, 2024). "In accordance with these findings, CDH17 RGD‐specific monoclonal antibodies (mAbs) inhibited the metastatic colonization in colorectal cancer and melanoma animal models." (PMID 33715292, 2021). "In colorectal cancer, cadherin-17 (CDH17) interacts with integrin α2β1 to activate FAK and Ras pathways promoting proliferation and metastasis." (PMID 33406733, 2021). "Previous studies underlined the inhibitory effect of CDH17 RGD‐specific mAbs in mouse models of liver and lung metastasis for colorectal cancer and melanoma, respectively." (PMID 33715292, 2021). "Genes elevated in colorectal cancer metastasis included higher expression of Cadherin 17 (CDH17) and the adhesion molecules CEACAM5 and CEACAM6, previously shown to correlate with metastasis colonization." (PMID 33332768, 2020). "In another study, the same group established a dual electrochemical immunoassay for the simultaneous detection of IL-13Rα2, as well as CDH-17, present in lysates from breast and colorectal cancer cells, respectively, with different metastatic potential." (PMID 31878102, 2019). "Cadherin-17 reportedly mediates significant increases in the adhesion and proliferation of highly metastatic human colorectal cancer cells, and cadherin-17 silencing in these cells suppresses tumor growth and liver metastasis." (PMID 28197418, 2017). "In the studies on many tumors, for example, gastric, ovarian, hepatocellular, and colorectal cancer, expression of cadherin-17 in human tissues was examined and estimated as an important candidate of prognosis marker." (PMID 28197418, 2017).